VIM (vimentin)
Diseases named in the same sentence as VIM in open-access papers (continued):
Sharing a sentence is not in itself a finding about the gene and the disease.
lung carcinoma (continued). "As an important cytokine, IL-6 has been observed to regulate EMT in cancers; therefore, we performed western blotting to detect MMP2/9, E-cadherin and vimentin expression in lung cancer cells treated with ADSC-CM or aADSC-CM." (PMID 31196220, 2019). "Vimentin is upregulated in various cancer diseases including malignant melanoma, prostate, breast, gastro-intestinal and lung cancer." (PMID 31827725, 2019). "The relative protein levels of BTBD7 (0.45 ± 0.16), FN (0.81 ± 0.24), and vimentin (0.42 ± 0.21) in lung cancer tissues were significantly higher (p < 0.05) than those in paracancer tissues (0.20 ± 0.09, 0.26 ± 0.16, and 0.15 ± 0.13, respectively)." (PMID 31886230, 2019). "Here, we first found that RASSF1C promotes the expression of β-catenin, vimentin, and snail in lung cancer cells." (PMID 30719208, 2019). "TGF-β1 is reported to activate p38 MAPK and Jun N-terminal kinase (JNK) in lung cancer cells to increase the expression of vimentin and decrease the expression of E-cadherin." (PMID 31547193, 2019). "Consistent with this, we found that treatment of lung cancer cells with miR-33a mimics decreased cell proliferation and expression of β-catenin, vimentin, and snail in lung cancer cells." (PMID 30719208, 2019). "KLF3 expression was negatively correlated with STAT3 and vimentin expression in the clinical lung cancer specimens." (PMID 31486564, 2019). "All experimental results showed that the levels of BTBD7, N-cadherin, fibronectin, and vimentin were increased in lung cancer tissues and cells, while the E-cadherin level was decreased." (PMID 31886230, 2019). "This possibility was also supported by close localization of the immunofluorescent signals for fibronectin and the mesenchymal cell marker vimentin in the lung cancer tissues." (PMID 30670761, 2019). "Specifically, a far-red fluorescent protein was knocked-in in-frame with the mesenchymal gene marker VIMENTIN (VIM) in H2170 lung cancer cells." (PMID 31847480, 2019). "In conclusion, our study demonstrated that CTCs from newly diagnosed advanced lung cancer patients were highly heterogeneous based on cell size, Chr8 aneuploidy and vimentin expression." (PMID 31646374, 2019). "Resveratrol was found to suppress the expression of EMT-inducing transcription factors such as SNAI1 and SLUG with concomitant increase in expression of E-cadherin along with suppression of vimentin and fibronectin in lung cancer cells." (PMID 31547193, 2019). "TEX isolated from the serum of late stage lung cancer patients, like highly metastatic lung cancer cells, contain high levels of vimentin and the TEX can induce EMT in recipient human bronchial epithelial cells." (PMID 29720982, 2018). "Herein, we demonstrate that 2-AP can restore E-cadherin expression and inhibit fibronectin and vimentin expression in TGF-β1–treated A549 lung cancer cells." (PMID 29531814, 2018). "In lung cancer, vimentin changes cancer cell adhesion by regulating the VAV2–Rac1 pathway and modifying focal adhesion kinase activity." (PMID 29720982, 2018). "An additional motile property of vimentin is seen within the leading edge of lung cancer cells, where vimentin can bind to and regulate focal adhesion kinase (FAK)." (PMID 30248895, 2018). "In lung cancer, vimentin expression has been seen in large-cell pulmonary carcinomas, and well-differentiated pulmonary adenocarcinomas." (PMID 30248895, 2018). "The genes of E-cadherin, vimentin, and N-cadherin in A549 lung carcinoma cells were selected as the objects of the experiment." (PMID 29467444, 2018). "We focused on some EMT markers specifically involved in lung cancer progression, and found that miR-140-3p restored the levels of E-cadherin while reduced the expression of N-cadherin, Vimentin, Slug and Snail." (PMID 30559931, 2018). "Several studies have provided evidence for the involvement of vimentin in the progression of various lung cancers." (PMID 30248895, 2018).
lung carcinoma (continued). "This is significant as Rac1 and vimentin are essential regulators of the cytoskeleton structure with control over the epithelial-mesenchymal transition, cell migration and metastasis of lung cancer." (PMID 30333761, 2018). "One study of patients with non–small-cell lung cancer showed that expression of vimentin and E-cadherin correlated with favourable patient outcome for erlotinib treatment, which suggested that vimentin has a role as a predictive biomarker for this therapy." (PMID 30248895, 2018). "CK+/Vimentin+/CD45- and CK-/Vimentin+/CD45- cell populations were also detected in blood samples from lung cancer patients with our method in addition to CK+/Vimentin-/CD45- cells." (PMID 28039472, 2017). "The data reported here hold great promise for the detection of CTCs from lung cancer patients, thus making Vimentin as a CTC marker." (PMID 28039472, 2017). "Oestradiol promoted lung cancer cell migration through downregulation of E-cadherin and β-catenin and upregulation of fibronectin and vimentin." (PMID 28717394, 2017). "To better understand the expressions of CK and Vimentin, we analyzed protein expression profiles of lung carcinoma cell lines (H446, SK-MES-1 cells and A549)." (PMID 28039472, 2017). "Vimentin expression has been detected in epithelial malignancies like prostate, breast, and lung cancer as well as in gastrointestinal and central nervous system tumors." (PMID 28421110, 2017). "Our results demonstrated that VPA sodium salt promoted expression of the EMT marker vimentin protein in lung cancer cells." (PMID 28881812, 2017). "We first examined typical features of the EMT such as decreases in E-cadherin expression, and increases in N-cadherin and vimentin protein levels in A549 lung cancer cells (A549-CUG2) and immortalized bronchial BEAS-2B cells (BEAS-CUG2) stably expressing CUG2." (PMID 27974707, 2017). "Studies have shown that lung cancer patients with history of smoking tobacco/cigarette exhibit lower expression levels of E-cadherin and higher levels of mesenchymal markers such as vimentin." (PMID 28651527, 2017). "Analyses of lung cancer blood samples revealed that three cell types of CK+/Vimentin-/CD45-, CK+/Vimentin+/CD45- and CK-/Vimentin+/CD45-CTC were existed in the blood of cancer patients." (PMID 28039472, 2017). "VJ treatment upregulated E-cadherin expression and reduced N-cadherin, β-catenin, Vimentin, and Slug expression in a time-dependent manner in both lung cancer cells." (PMID 29234489, 2017). "We found that CAFs induced EMT in lung cancer cells characterized by decreased E-cadherin level and increased vimentin level." (PMID 29100297, 2017). "We also showed that exosomes derived from late stage lung cancer serum have higher vimentin expression and induced a metastatic phenotype in recipient cells." (PMID 27363026, 2016). "Accumulating evidence indicates that vimentin is critical for the progression and prognosis of lung cancer." (PMID 27657690, 2016). "It was shown that activation of PPAR-γ inhibits TGF-β-induced loss of E-cadherin expression, the induction of mesenchymal markers (vimentin, N-cadherin, fibronectin), MMPs and antagonizes Smad3 function, thereby preventing metastasis in lung cancer." (PMID 27092172, 2016). "The further study showed that down-regulating FUT4 increased E-cadherin, and decreased Snail, N-cadherin and Vimentin in lung cancer cells, and thus, hindering EMT." (PMID 26636541, 2016). "We demonstrated that vimentin expression was up-regulated in lung cancer serum derived exosome treated HBECs compared to healthy serum exosome treated HBECs." (PMID 27363026, 2016). "Nicotine can activate the Wnt3a signal pathway in lung cancer cells, leading to an upregulation of several mesenchymal markers such as vimentin, matrix metalloproteinases-9, and type I collagen as well as downregulation of E-cadherin." (PMID 27077888, 2016).
lung carcinoma (continued). "Radiation induced EMT in lung cancer cells and xenografts, as evidenced by increased expression of the mesenchymal markers N-cadherin and Vimentin, and reduced expression of the epithelial markers E-cadherin and Cytokeratin." (PMID 27533085, 2016). "Vimentin expression at the messenger level was significantly higher in exosomes derived from late stage lung cancer serum compared to healthy and early stage lung cancer serum." (PMID 27363026, 2016). "In order to assess for the internalization of exosomes in recipient HBECs and the effect on vimentin expression, exosomes isolated from human healthy and lung cancer serum were stained with PKH67 (green) dye and applied to HBECs." (PMID 27363026, 2016). "The current study is the first investigation to focus on the correlations between vimentin and the prognosis and clinicopathological characteristics of lung cancer using a meta-analysis, and the results of this analysis are meaningful." (PMID 27657690, 2016). "Consistent with previous reports, we found that HGF stimulated the phosphorylation of c-Met followed by an increase in the levels of vimentin and decrease of E-cadherin in lung cancer A549 and 95D cells." (PMID 26919096, 2016). "We found that exosomes derived from highly metastatic lung cancer cells and human late stage lung cancer serum induced vimentin and EMT in recipient cells." (PMID 27363026, 2016). "It is possible that exosomes from metastatic lung cancers contain higher vimentin (as our data suggests) and that exosomes induce vimentin in normal epithelial cells." (PMID 27363026, 2016). "We found that exosomes derived from highly metastatic lung cancer cells and human late stage lung cancer serum induced vimentin expression, and epithelial to mesenchymal transition (EMT) in HBECs." (PMID 27363026, 2016). "Vimentin expression was higher both at messenger and protein levels in lung cancer serum exosome treated HBECs compared to healthy serum exosome treatment." (PMID 27363026, 2016). "In the present study, we demonstrated that astrocyte elevated gene-1(AEG-1) ectopic overexpression promoted EMT, which resulted from the down-regulation of E-cadherin and up-regulation of Vimentin in lung cancer cell lines and clinical lung cancer specimens." (PMID 25880337, 2015). "Overexpression of DAL-1 altered the expression of numerous EMT markers, such as E-cadherin, β-catenin Vimentin and N-cadherin expression, meanwhile changed the morphological shape of lung cancer cells, and whereas silencing DAL-1 had an opposite effect." (PMID 25609022, 2015). "Spearman rank correlation analysis was applied to analyze the expression levels of DAL-1, E-cadherin, Snail, vimentin in lung cancer tissues." (PMID 25609022, 2015). "Although AEG-1 is an oncogene that has been implicated in pathways critical to lung cancer carcinogenesis, AEG-1 was also found to control the expression of E-cadherin and Vimentin." (PMID 25880337, 2015). "Biomarkers specifically reflecting degradation of collagen type I and citrullinated vimentin are applicable for lung cancer patients." (PMID 25044252, 2014). "After screening twenty human lung cancer cell lines through expression patterns of E-cadherin and vimentin according to epithelial mesenchymal transition features, an H1975 cell line carrying EGFR mutations, L858R and T790M, was selected for investigation." (PMID 25462870, 2014). "It is an upstream regulator of the PI3K/Akt/NFκB pathway in esophageal, head and neck, ovarian, gastric and lung cancer cells, and the expression of vimentin and fibronectin is regulated by Id1 at transcriptional level in NSCLC." (PMID 24970809, 2014). "It appears lung cancer tissues with cytoplasmic/nuclear localization of p120ctn tended to express vimentin in comparison with those with the membranous localization (41.2% [21/51] versus 14.8 [4/27]).." (PMID 24505377, 2014).
lung carcinoma (continued). "We demonstrated that after prolonged NO exposure, the lung cancer H23 cells increased the expression level of vimentin and snail in concomitant with the decrease of E-cadherin." (PMID 24967418, 2014). "We further detected the expression levels of p120ctn, E-cadherin and vimentin in lung cancer cells by Western blot and screened cell lines expressing both low and high levels of p120ctn and with E-cadherin in the membrane or cytoplasm." (PMID 24505377, 2014). "After indirect co-culture for 8 days, lung cancer cells exhibited similar expression of E-cadherin, vimentin, α-SMA and fibronectin in all three NSCLC cell lines compared with parental lung cancer cells that were cultured alone (data not shown)." (PMID 24516569, 2014). "This study showed that IL-27 treatment in lung cancer cells led to increased E-cadherin expression and decreased expression of vimentin and Snail with inhibition of cell migration by suppression of cyclooxygenase-2-mediated activities." (PMID 24274066, 2013). "E2 promoted lung cancer cell migration through downregulation of E-cadherin and β-catenin and upregulation of fibronectin and vimentin." (PMID 24222765, 2013). "Vimentin, which is known to be overexpressed in lung cancer and correlated well with accelerated tumor growth and invasion, remained unchanged in MCME-treated CL1 cells." (PMID 23320038, 2012). "The signature was derived from an analysis of 93 lung cancer cell lines that had been previously globally molecularly profiled and sorted by two genes associated with the EMT phenotype, CDH1 and VIM." (PMID 21251323, 2011). "Upregulation of vimentin has been reported in prostate cancer, lung cancer and carcinosarcoma and vimentin have been used as a marker for lung cancer detection." (PMID 19367286, 2009). "Notably, nicotine elicits an upregulation of α5-nAChR, Ly6E, phosphorylated Smad3 (pSmad3), Zeb1, N-calmodulin, and vimentin in lung cancer cells." (PMID 40143965, 2025). "DNMT1 is able to mediate the CpG islands methylation, thereby controlling the promoter methylation of the tumor suppressor gene FHIT in cancer cells, thereby inducing an increase in the expression of MMP-9 and vimentin, and promoting the invasive metastasis of lung cancer." (PMID 40143965, 2025). "Recently, wildtype vimentin has been shown to increase malignant progression in lung cancer." (PMID 40690373, 2025). "A previous study demonstrated that vimentin is required for lung cancer metastasis." (PMID 38388902, 2024). "In addition, depletion of vimentin in lung cancer A549 cells largely prevented nuclear dysmorphia during the epithelial-to-mesenchymal transition induced by TGFβ." (PMID 39542246, 2024). "This cytokeratin upregulates the synthesis of vimentin in lung cancer cells." (PMID 39737401, 2024). "To further clarify whether the EMT and PD-L1 expression were also affected, we detected the levels of E-cadherin, vimentin, and PD-L1 in lung cancer cells from the different co-culture groups by immunofluorescence assay." (PMID 38340166, 2024). "Moreover, SMAD3 knockdown suppresses the migration and invasion of lung cancer cell line, and the expression of VIM and CDH2 was decreased by SMAD3 knockdown." (PMID 37121971, 2023). "In addition, it was shown that exosomes obtained from the sera of patients with advanced lung cancer had increased expression of VIM and induced a more metastatic phenotype in recipient cells, suggesting that exosomes can trigger EMT of lung cancer cells." (PMID 37122754, 2023). "In addition, we also observed that JFD significantly increased E-cadherin protein and decreased N-cadherin and vimentin protein levels in lung cancer cells." (PMID 38104091, 2023).
lung carcinoma (continued). "Therefore, vimentin overexpression can be a potential marker for predicting metastasis and can serve as an attractive potential therapeutic strategy for invasive lung cancer." (PMID 35684095, 2022). "Meanwhile, the delivery of lung cancer EVs-miR-122-5p promoted hepatocyte migration by increasing the expression of N-cadherin and vimentin, which plays an important role in the establishment of the pre-metastatic microenvironment in lung cancer and liver metastasis." (PMID 36139427, 2022). "MTAP and PRMT5 negatively correlate with vimentin in lung cancer samples." (PMID 35766227, 2022). "Herein, coriloxin treatment downregulated lung cancer cells’ vimentin and N-cad expression." (PMID 35409350, 2022). "Previous studies have shown that vimentin regulates cell-ECM association by controlling the size of focal adhesions through interacting with integrin β1 and β3, vimentin also increases lung cancer cell adhesion by stabilising FAK-positive focal adhesions through activating Rac1." (PMID 36552797, 2022). "We then examined whether the vimentin responded differently within sensitive and resistant lung cancer cells upon attack by NK cells." (PMID 36032170, 2022). "Recent studies also indicate that ΔNp63 isoform of p63, also regulates collective invasion package (CIP) during lung cancer metastasis, and Vimentin is required for CIP, which is also poor prognostic indicator in lung adenocarcinoma cells, compatible with our findings in this research." (PMID 35201505, 2022). "Compared with untreated CAF-CM, autophagy-inhibited CAF-CM abrogated CAFs’ effect on EMT status of lung cancer cells, evidenced by upregulation of mesenchymal markers N-cadherin and vimentin, downregulation of epithelial marker E-cadherin at both mRNA and protein levels." (PMID 34552063, 2021). "Meanwhile, vimentin expression was positively correlated with CD8+ T cells number in lung cancer." (PMID 34158591, 2021). "The same results were observed for lung cancer lines (A549) where treatment with TGF-β1 significantly decreased the gene expression of CDH1 (encoding E-cadherin), increased the gene expression of ACTA2 (encoding α-SMA) and VIM (encoding vimentin)." (PMID 33673178, 2021). "Increased level of vimentin and decreased level of E-cadherin was evident in lung cancer cells." (PMID 34395245, 2021). "We found that OPN‐PI3K or OPN‐MEK pathways could play critical roles in regulation of EMT development and migration/movement of lung cancer cells through the regulation of vimentin‐dependent signals." (PMID 34323425, 2021). "Similarly, exosomes derived from lung CSCs promote EMT, migration, and invasion of lung cancer cells by upregulating the expression levels of N-cadherin, Vimentin, MMP-9, and MMP-1, and downregulating the expression of E-cadherin." (PMID 34511114, 2021). "In vitro, EGCG has been shown to inhibit growth by increasing the percentage of cells at the G0/G1 phase of the cell cycle and inhibit epithelial-mesenchymal transition and migration via downregulation of HIF-1α, VEGF, pAkt/ERK, COX-2 and vimentin in A549 lung cancer cell." (PMID 34650434, 2021). "In agreement with the correlation analysis between β3 integrin and EMT markers, β3 integrin-overexpressing lung cancer cells showed increased mesenchymal markers, including N-cadherin, vimentin, and ZEB1; however, only small reductions were observed in E-cadherin, OVOL1, and ZO-1." (PMID 33883697, 2021). "miR-3591-5p inhibition has been proven effective in preventing the effects of the radiation regarding morphological changes in cells, the expression of the mesenchymal markers vimentin and α-smooth muscle actin, and the activation of TGFβ signaling in lung cancer." (PMID 33498521, 2021).